CRP (C-reactive protein)
Diseases named in the same sentence as CRP in open-access papers (continued):
Sharing a sentence is not in itself a finding about the gene and the disease.
malaria (continued). "Changes in levels due to inflammation, as shown with CEBPA, CRP and CCL5 protein levels, were more exacerbated in the CM than the DC samples suggesting a stronger inflammatory response in malaria-infected patients than in other diseases." (PMID 24743550, 2014). "In addition, there may be another pitfall with CRP-based decision rules in malaria." (PMID 22221299, 2012). "Hpr levels were measured, together with Hp and the acute phase proteins, C-reactive protein (CRP) and albumin, in a large cohort of children living in a malaria-endemic area of Gabon." (PMID 23185445, 2012). "The remaining 890 febrile episodes were classified as not being due to malaria; of these, 27 (3%) were associated with a positive result for a malaria dipstick test, but in these cases, fever could not be confirmed and plasma C-reactive protein concentration was < 8 mg/L." (PMID 21939508, 2011). "A recent study in Malawi shows that PCT and CRP in presence of bacterial pneumonia/meningitis were elevated in both HIV-uninfected and infected children, but data on malaria in this study were poor." (PMID 20976241, 2010). "Presence of malaria parasites should be taken into consideration, either for clinical or epidemiological purposes, if using PCT or CRP to differentiate viral from invasive bacterial pneumonia in malaria-endemic areas." (PMID 20976241, 2010). "Only one malaria-negative child had chronic inflammation (AGP = 1.5 g/L) but no acute inflammation (CRP = 2.2 mg/L)." (PMID 40277833, 2025). "The results of the comparison of means of the levels of AGP, CRP, and IgG4 revealed significant differences between malaria-positive and malaria-negative children." (PMID 40277833, 2025). "Basic disease knowledge for malaria was excellent (100% correct), but CRP knowledge was lacking, with 50% unaware that a raised CRP value indicates a higher probability that an infection is of bacterial origin." (PMID 40340660, 2025). "Several other biomarkers, such as CRP, Ang-1, Ang-2, and PCT, show potential for malaria detection in terms of their ability to differentiate disease severity, and the levels of these biomarkers can be determined in the body for comparison with malaria parasitemia." (PMID 39997008, 2025). "Circulating biomarkers like C-reactive protein (CRP) and soluble TNF receptors may be elevated in severe malaria cases, indicating systemic inflammation." (PMID 38694310, 2024). "Participants who tested positive for malaria by mRDT on average had higher CRP levels than those who tested negative." (PMID 38241274, 2024). "The mean CRP (SD) as measured using the Afinion assay in malaria positive and malaria negative patients was 20.5 (2.8) mg/L and 58.9 (8.8) mg/L, respectively." (PMID 38241274, 2024). "All patients with positive results for raised CRP or acute dengue were referred to the local health centres for further management, and all malaria cases were managed by VMWs with or without onward referral based on existing practices." (PMID 38166839, 2024). "This suggests that CRP is less effective than RDTs in predicting malaria, and should not be used for this purpose." (PMID 37478118, 2023). "Negative predictive values (NPV) represent the proportion of true negatives among negative patients, as defined by CRP < 23.6mg/L for malaria and < 36.2mg/L for bacterial infection." (PMID 37478118, 2023). "These values, taken globally, would suggest that a negative CRP (defined as <24mg/L for malaria and <36mg/l for bacterial infection), is usually correct in excluding malaria and bacterial infection in a febrile child." (PMID 37478118, 2023). "The waiting time was a concern for the respondents in the DPP groups, but not by the Dengue Duo and Malaria/CRP Duo groups." (PMID 37317948, 2023). "On the other hand, a positive CRP (defined as >24mg/L for malaria and >36mg/l for bacterial infection) is not enough to predict malaria in a febrile child on its own." (PMID 37478118, 2023).
malaria (continued). "As expected, CRP levels were higher in malaria-positive than in malaria-negative patients—which makes CRP unsuited for distinguishing between bacterial and nonbacterial concomitant infections in the presence of malaria." (PMID 37490743, 2023). "In terms of laboratory parameters, children with malaria were more frequently anaemic and thrombocytopenic on admission and showed higher serum levels of CRP compared to those without parasitaemia." (PMID 37087435, 2023). "For example, CRP and platelet count exhibited interesting performances of malaria severity in nonimmune European patients as well as in individuals from malaria endemic areas (India, Sudan, Nigeria, Senegal, and Malawi)." (PMID 36036460, 2022). "A 2014 meta-analysis exclusively reported iron-malaria interactions when CRP-corrected ferritin levels, but not other markers, were used to determine maternal iron stores." (PMID 35619134, 2022). "Muriuki found that children with malaria had greater ferritin concentrations at every decile of CRP, compared with those without malaria." (PMID 35260210, 2022). "Even in the lowest decile of CRP, the difference in ferritin between children with malaria and without malaria was of about 20 μg/l." (PMID 35260210, 2022). "In high malaria-endemic areas, the combined testing of febrile cases with mRDT-PfHRP2 and CRP RDT is only useful in case both tests are negative and a malaria infection can be excluded." (PMID 36536340, 2022). "Several studies included in this review report that not all children with asymptomatic malaria have elevated CRP or AGP." (PMID 35260210, 2022). "An exception was the sub-analysis among malaria negative patients where both CRP and PCT had one less false positive case compared to the IMS." (PMID 33647009, 2021). "In comparison with negative patients with fever, patients with malaria have a smaller odds ratio (OR 13.84, CI 8.70–21.80) to present CRP greater than 27.65 mg/L." (PMID 34565334, 2021). "Data are presented separately for malaria positive cases, malaria negative cases and all cases, and compared to accuracy of CRP and PCT." (PMID 33647009, 2021). "Among the four study villages, Mhenda-Kitunduweta (Kilosa) was the village with the highest prevalence of stunting (34.8%), elevated acute phase proteins (40% with high CRP or AGP), and reported recent infection diseases (26% with diarrhoea, and 51% with malaria)." (PMID 34066852, 2021). "On the other hand, a study from Muheza district, Tanzania performing point-of-care tests (CRP and white blood cells) on malaria negative, febrile children concluded that assessment of white blood cell counts had limited value for detecting bacterial disease." (PMID 34176486, 2021). "Malaria with bacterial co-infection produced slightly, though not significantly (p = 0.07) higher CRP plasma levels (72 mg/L, IQR 34–107, n = 43) compared to malaria alone (51 mg/L, IQR 22–100, n = 180), with considerable overlap between the two." (PMID 33647009, 2021). "Data are separately presented for malaria positive cases, malaria negative cases and all cases, and compared to accuracy of CRP and PCT." (PMID 33647009, 2021). "Just like for the IMS, the accuracy of CRP and PCT was lower in patients with malaria." (PMID 33647009, 2021). "The human malaria array (5-Plex) was developed to provide quantitative measurement of the malaria antigens HRP2, PfLDH, and PvLDH and a qualitative measure for all malaria species (PanLDH) as well as measure the human biomarker CRP." (PMID 34781260, 2021). "Diagnostic accuracy of the IMS to detect all bacterial infections versus standard microbiological techniques among patients of all ages, presented for malaria positive cases, malaria negative cases and all cases, and compared to accuracy of CRP and PCT." (PMID 33647009, 2021). "Ferritin levels were highest in SA children without malaria, whereas CRP was highest in the group with parasitemia and lowest in SA children without malarial infection." (PMID 32901609, 2020).
malaria (continued). "Children with malaria also had higher ferritin concentrations at every decile of CRP, compared to those without malaria." (PMID 32102669, 2020). "Path modelling confirmed seasonal malaria effects on preterm birth, with mediation through C-reactive protein and (non-linear) hepcidin induction." (PMID 31771607, 2019). "C-reactive protein (CRP), a human inflammation marker, has been investigated as a biomarker to differentiate, in combination with malaria diagnosis, viral from nonviral infection in febrile case management." (PMID 30404944, 2019). "Elevated serum hepcidin and C-reactive protein concentrations were present in malaria parasitaemic, compared to non-parasitaemic, women in the trial." (PMID 31771607, 2019). "C-reactive protein (CRP), an acute phase reactant, whose plasma concentration increases during inflammatory disorders, has gained considerable attention as a biomarker in malaria." (PMID 31089391, 2019). "Few patients with negative CRP were malaria positive (7.1%), whereas more than half of patients with an increased CRP concentration (≥ 10 mg/l) were malaria positive (OR 14.5 [CI 4.4–47.6], p<0.001)." (PMID 30080904, 2018). "This work is sited around similar setting in the Upper East region and therefore the high CRP is not surprising because samples were collected throughout the year during some point when malaria or P. Falciparum parasitaemia is high." (PMID 29975702, 2018). "The semi-quantitative method of measuring CRP is cheap, rapid and easy to perform, but not useful in predicting malaria or parasitemia in febrile children." (PMID 30080904, 2018). "Negative predictive values of elevated CRP were high for parasitemia (92.9%) and malaria (97.0%), implying that the likelihood that patients with normal CRP levels have no parasitemia or malaria is high." (PMID 30080904, 2018). "The semi-quantitative method of measuring CRP is cheap, rapid and easy to perform but not useful in predicting parasitemia and malaria." (PMID 30080904, 2018). "CHI3L1 levels also correlated with markers of immune activation (CRP, sTREM-1, CXCL10/IP-10), endothelial activation (Ang-2, sICAM-1), and haemolysis (LDH, haem, haemopexin), pathways of injury that are well described in paediatric severe malaria." (PMID 29448936, 2018). "Sensitivity, specificity as well as positive predictive and negative predictive values of CRP for malaria were 99.3% (CI 96.2%-100%), 9.2% (CI 6.4%-12.8%), 31.7% (CI 27.4%-36.1%) and 97.0% (CI 84.2%-99.9%), respectively." (PMID 30080904, 2018). "Women who reported having malaria within the previous two months had a 1.9 times greater geomean CRP (15.31 mg/L) compared to women who did not have recent malaria (7.99 mg/L, p < 0.001)." (PMID 29986492, 2018). "CRP and AGP normalized faster than ferritin after malaria episodes." (PMID 30537973, 2018). "Accordingly, in patients with elevated CRP levels, about a half had no parasitemia and two-thirds had no malaria." (PMID 30080904, 2018). "There appeared to be no added effect of both elevated AGP and CRP (the early convalescent stage) on sTfR concentrations irrespective of malaria status." (PMID 28615256, 2017). "Adjustment for malaria in addition to CRP and AGP did not substantially change the estimated prevalence of depleted iron stores." (PMID 28615259, 2017). "There was no added effect of adjusting for malaria on the estimated VAD after adjusting for CRP and AGP." (PMID 28615251, 2017). "In this study, we found that the measurement of white blood cells and CRP did not facilitate diagnosis of bacterial illness in children with malaria‐negative fever in Tanzania." (PMID 27935664, 2017). "Individuals who were stratified by malaria status (as a dichotomous variable) and by the 4-inflammation groups had the highest ferritin concentrations in the group with malaria and elevated CRP and AGP in PSC but not in WRA." (PMID 28615259, 2017).
malaria (continued). "Thus, when both AGP and CRP are measured, there appears to be limited utility in adjusting TBI for malaria status." (PMID 28615255, 2017). "However, adjusting for inflammation with the use of IRC accounting for both CRP and AGP resulted in similar point estimates of estimated VAD as when adjusting for malaria and inflammation both." (PMID 28615251, 2017). "We analyzed NFS, the lipid profile, CRP and LDH in a series of 30 cases of malaria." (PMID 28674567, 2017). "Notwithstanding these questions, this analysis provides further support to the possible implementation of CRP rapid tests at point-of-care, in order to inform the management of febrile patients with a negative malaria test." (PMID 26846919, 2016). "The children in this cohort did not reside in a malaria endemic area and based on CRP concentrations did not have a high prevalence of inflammation, both of which are likely to impact significantly on hepcidin concentrations." (PMID 27332551, 2016). "During malaria, a negative correlation (r = −0.352, P = 0.011) between CRP and TAP was rather found in the control group only." (PMID 27298824, 2016). "Interestingly, the two groups differed in their extent of elevation of CRP and peroxides but their extent of decrease in TAP levels during malaria was equal." (PMID 27298824, 2016). "In this study we estimate the diagnostic accuracy of two well established biomarkers of bacterial infection, procalcitonin and C-reactive protein (CRP) in discriminating between common viral and bacterial infections in malaria endemic settings of Southeast Asia." (PMID 26558692, 2015). "Notably, the most significant candidates differing between controls and malaria groups were major inflammatory components von Willebrand factor (VWF) and C-reactive protein (CRP)." (PMID 24743550, 2014). "The role of CRP in malaria is not clear but CRP levels are known to be highly elevated in acute stages of the disease." (PMID 23922912, 2013). "Using binary logistic regression analysis, schizontaemia was found to be an independent predictor for severe malaria with odds ratios substantially exceeding that found for C-reactive protein and lactate but not that found for parasite load." (PMID 22929647, 2012). "C-reactive protein but not copeptin was found to be an accurate predictor for disease severity in imported malaria." (PMID 22221299, 2012). "Giemsa-stained thick blood films were negative for malaria parasites and plasma C-reactive protein, blood lactate, white cell count and blood culture results did not suggest an acute infective aetiology." (PMID 21245918, 2011). "Patients with symptomatic malaria presented with higher levels of AST, ALT, total bilirubin and CRP compared to both asymptomatic malaria and non-infected individuals." (PMID 21625634, 2011). "However, in presence of malaria parasites distribution between clinical groups overlapped (PCT: median = 23.1 vs. 21.75 ng/ml, p = 0.825; CRP: median = 96.8 vs. 217.4 mg/l, p = 0.052)." (PMID 20976241, 2010). "Our main finding is that PCT and CRP can not differentiate between these two clinical groups among hospitalized children with malaria parasites." (PMID 20976241, 2010). "Thus, CRP cannot be classified as an ideal biomarker for malaria detection due to its lack of specificity." (PMID 39997008, 2025). "CRP is not a specific biomarker for malaria detection but can be used to determine whether or not CRP levels are normal in patients." (PMID 39997008, 2025). "Similarly, for CRP, the mean concentration was also lower in malaria-negative children (3.02 mg/L) compared to the malaria-positive children (28.61 mg/L), with a mean difference of 25.58 (95% CI: −32.556 to −18.621) and a t-value of −7.312 (p < 0.001)." (PMID 40277833, 2025). "Therefore, normal CRP levels can be used to exclude malaria if microscopy and RDTs are not available." (PMID 39997008, 2025). "Among malaria patients, CRP levels were independent of parasitemia." (PMID 37478118, 2023).
malaria (continued). "Positive and negative values for CRP and malaria using optimal cut-off." (PMID 37478118, 2023). "The previous study suggested that serum IL-12 levels and other cytokines such as TNF-α, IFN-γ, and CRP levels might not be candidate markers for severe malaria because of the absence in the difference in their levels in higher parasite densities." (PMID 35954703, 2022). "Point-of-Care C-Reactive Protein (POCCRP) tests could distinguish between bacterial and non-bacterial causes of fever in malaria-negative patients and thus reduce inappropriate antibiotic prescribing." (PMID 34748558, 2021). "The null hypotheses of equality of medians were not rejected when comparing the CRP values between malaria species (p-value = 0.526), nor in patient sex of each malaria specie group." (PMID 34565334, 2021). "However, the meta-analysis demonstrating the possibility of CRP as an early marker for malaria infection and malaria severity has not been investigated." (PMID 34764364, 2021). "We found that children with malaria parasitemia had higher concentrations of hepcidin, above a threshold blocking iron absorption, at almost every decile of CRP compared to levels in children without malaria, and this effect was observed regardless of the presence of inflammation." (PMID 33619371, 2021). "Because CRP is usually measured using a rapid, simple, nonspecific, routine laboratory test, CRP levels might be useful in assisting with the early detection of malaria and determining malarial severity." (PMID 34764364, 2021). "However, in a setting like sub-saharan Africa where other febrile illnesses play an important role, a negative CRP can nearly rule out parasitemia or malaria due to its high negative predictive value." (PMID 30080904, 2018). "Nevertheless, a negative CRP has a high negative predictive value in few patients with normal CRP, meaning a negative CRP might be indicative of those patients unlikely to be presenting with clinical malaria." (PMID 30080904, 2018). "Malaria was significantly associated with elevated CRP and elevated AGP, whereas rural location was significantly associated with elevated AGP but not with elevated CRP." (PMID 28615263, 2017). "Moreover, laboratory data, which included leukocyte counts, haemoglobin, platelets, and C-reactive protein, had no statically significant differences in malaria patients and ABO blood types." (PMID 29238723, 2017). "There was no multicollinearity between ln-CRP and ln-AGP or between ln-CRP, ln-AGP, and malaria, although the larger negative slopes that were seen in the bivariate regression compared with the multiple regression were likely due to ln-CRP and ln-AGP being correlated." (PMID 28615251, 2017). "Regarding the use of CRP to guide the use of antibiotics in febrile patients with a negative malaria test, this study confirms that plasma CRP concentrations in this rural, Southeast Asian population were above a conservative threshold of 10mg/L in only 4.6% of individuals." (PMID 27386859, 2016). "However, distribution between clinical groups has been shown to overlap in presence of malaria parasites, suggesting that malaria infection should be taken into consideration if using PCT or CRP to differentiate viral from invasive bacterial pneumonia in malaria-endemic areas." (PMID 26979504, 2016). "Despite the fact that the qualitative RDT used for malaria diagnosis in the current study could not determine degree of infection directly, a number of earlier reports have observed that CRP levels increase with increased falciparum parasitaemia." (PMID 27298824, 2016). "For malaria infected individuals (M and CI) the profile was high levels of IL-1β, IL-6, TNF-α IL-10, and CRP and decreased levels of IL-17A while for malaria negative individuals (IP and UN) the profile was high levels of IL-17A, NO and decreased levels of IL-10 and CRP." (PMID 25309052, 2014).